DEPTOR (DEP domain containing MTOR interacting protein)
Diseases named in the same sentence as DEPTOR in open-access papers (continued):
Sharing a sentence is not in itself a finding about the gene and the disease.
prostate carcinoma (10 papers, 2014 to 2025). A carcinoma that arises from epithelial cells of the prostate gland. "Since we have previously shown that SAG knockdown causes DEPTOR accumulation to block mTORC signaling in prostate cancer cells, we focused our study on CDH1." (PMID 36548081, 2023). "Paradoxically, amplification of DEPTOR has been shown to correlate with worse progression-free survival, while a reduction in DEPTOR protein and mRNA transcript levels has also been implicated with prostate cancer progression." (PMID 33105713, 2020). "Taken together, our results suggest that DEPTOR depletion or knockdown promotes the proliferation and survival of prostate cancer cells, which is accompanied by the activation of mTORC1 and mTORC2 signals." (PMID 31685947, 2020). "Given that DEPTOR expression is decreased in human prostate cancer tissues, we next determined the role of DEPTOR in the proliferation and survival of prostate cancer cells." (PMID 31685947, 2020). "With the exception of DEPTOR gene amplification, genetic alterations to mTORC1/2 components are relatively infrequent in prostate cancer." (PMID 33105713, 2020). "Here we showed that the levels of both DEPTOR protein and mRNA were substantially decreased in human prostate cancer tissues, which positively correlated with disease progression." (PMID 31685947, 2020). "In this study, we report that DEPTOR expression was significantly decreased in human prostate cancer tissues at both the protein and mRNA levels, and positively correlated with prostate cancer progression." (PMID 31685947, 2020). "Third, elucidation of the mechanism by which DEPTOR is downregulated in prostate cancer would provide a new strategy to reactivate DEPTOR to slow down the disease progression." (PMID 31685947, 2020). "DEPTOR depletion accelerated proliferation and survival, migration, and invasion in human prostate cancer cells." (PMID 31685947, 2020). "Furthermore, systemic deletion of Deptor in a Pten+/− transgenic mouse was shown to promote prostate tumorigenesis accompanied with increased mTORC1/2 signaling, suggesting that the restoration of DEPTOR could be a beneficial therapeutic approach for PTEN-deficient prostate cancer." (PMID 33105713, 2020). "Statistical analysis by Wilcoxon rank sum test between the IHC scores of prostate tumor tissues and corresponding tumor-adjacent normal tissues showed that DEPTOR expression was significantly decreased in prostate cancer (p = 0.041)." (PMID 31685947, 2020). "DEPTOR depletion promoted proliferation, survival, cell migration, and invasion of prostate cancer cells, as a result of mTORC1 and mTORC2 activation." (PMID 31685947, 2020). "Taken together, these results suggest that the increase of Snail likely plays a major role in promoting EMT in prostate cancer cells upon DEPTOR depletion." (PMID 31685947, 2020). "In this study, using human prostate cancer tissues and cell culture, as well as mouse KO model, we showed that DEPTOR plays a tumor suppressive role in the prostate by inactivating both mTORC1 and mTORC2 signals." (PMID 31685947, 2020). "This notion was further supported by our rescued experiment in which simultaneous knockdown of either PHLPP1 or DEPTOR largely abrogated the growth suppression triggered by SAG knockdown in DU145 prostate cancer cells." (PMID 27955654, 2016). "mTORC1 stimulates transcription and translation and contains several proteins, including the regulatory-associated protein of mTOR (RAPTOR) and the DEP domain-containing mTOR-interacting protein (DEPTOR), which is often overexpressed in late-stage prostate cancer." (PMID 36768610, 2023). "Similarly, through the inhibition of mTORC1/2 signals, DEPTOR serves as a tumor suppressor in human prostate cancer." (PMID 35095893, 2021). "Taken together, DEPTOR reduction in prostate cancer tissues and its correlation with disease progression suggest that reduced DEPTOR expression could contribute to the development of human prostate cancer." (PMID 31685947, 2020).
prostate carcinoma (continued). "Thus, DEPTOR inhibits prostate tumorigenesis by inactivating mTOR signals, suggesting the potential use of mTOR inhibitors to treat prostate cancer with low DEPTOR expression." (PMID 31685947, 2020). "mTOR inhibitors should reactivate DEPTOR, particularly in prostate cancer with low DEPTOR expression; Second, DEPTOR is subjected to ubiquitylation by SCFβTrCP E3 ubiquitin ligase for proteasome degradation, thus inhibition of SCF E3 by MLN4924 should cause DEPTOR accumulation." (PMID 31685947, 2020). "Thus, DEPTOR reactivation via a variety of means would have therapeutic potential for the treatment of prostate cancer." (PMID 31685947, 2020). "We speculated that although S6K activation suppresses AKT, as often seen in many other types of cells, in prostate cancer cells with DEPTOR depletion, AKT activation by overactivated mTORC2 could neutralize or counteract S6K effect." (PMID 31685947, 2020). "Thus, cell migration and invasion stimulated by DEPTOR depletion are likely due to the enhanced EMT in prostate cancer cells." (PMID 31685947, 2020). "To gain mechanistic insight into SAG action, we used the loss-of-function approach in two human prostate cancer cell lines and found that SiRNA-based SAG knockdown caused in general accumulation of PHLPP1 and DEPTOR with consequential inactivation of pAKT and mTORC1 activity." (PMID 27955654, 2016). "Thus, the discovery of small molecules that can restore DEPTOR expression to inactivate mTOR/AKT signaling might be an attractive approach for future anti-prostate cancer therapy." (PMID 31685947, 2020). "Thus, we next chose DU145 and 22RV1 cells to generate DEPTOR depleted cells via a CRISPR/Cas9-based approach and found that DEPTOR depletion significantly promoted cell proliferation in two individual colonies of sgDEPTOR cells in both prostate cancer cell lines, compared with that in sgCtrl cells." (PMID 31685947, 2020). "Therefore, further studies on the association of DEPTOR and NPC2 with prostate cancer are needed." (PMID 24800880, 2014). "First, we measured the levels of DEPTOR in multiple prostate cancer cells and found that DU145 and 22RV1 cells have high expression of DEPTOR and low phosphorylation of S6K1 and AKT." (PMID 31685947, 2020). "Consistently, SAG knockdown suppressed the growth and survival of human prostate cancer cells due to accumulation of PHLPP1 and DEPTOR, two new substrates of SAG E3 ligase, which can be partially rescued by simultaneous knockdown of PHLPP1 or DEPTOR." (PMID 27955654, 2016). "Collectively, our results suggested that SAG knockdown triggers accumulation of PHLPP1 and DEPTOR to inactivate the AKT/mTOR axis, leading to observed suppression of growth and survival in prostate cancer cells." (PMID 27955654, 2016). "The antibody specificity was further confirmed by complete lack of DEPTOR staining in prostate cancer cells transfected with sgDEPTOR, and in vivo xenografts, derived from cells with shDEPTOR transfection." (PMID 31685947, 2020). "Interestingly, in our study, overactivation of S6K1 upon DEPTOR depletion in prostate cancer cells and mice tissues did not inactivate PI3K/AKT signal." (PMID 31685947, 2020).
lung carcinoma (9 papers, 2017 to 2025). "The UBE2C/CDH1/DEPTOR axis forms an oncogene and tumor suppressor cascade regulating autophagy and cell cycle, and UBE2C is a lung cancer target associated with Kras mutations." (PMID 40650277, 2025). "Taken together, our study identified an E2/E3 pair for DEPTOR ubiquitylation and degradation, and validated UBE2C as a promising target for lung cancer associated with Kras mutations." (PMID 36548081, 2023). "This notion is further supported by the observation that DEPTOR levels were increased in lung cancer cell lines upon UBE2C knockdown, and in lung tumor tissues derived from Ube2c-deleted mice." (PMID 36548081, 2023). "Taken together, our study shows that the UBE2C/CDH1/DEPTOR axis forms an oncogene and tumor suppressor cascade that regulates cell cycle progression and autophagy and validates UBE2C an attractive target for lung cancer associated with Kras mutations." (PMID 36548081, 2023). "However, it should be noted that other pathways are likely involved, given the observation of partial rescue by DEPTOR knockdown in lung cancer cells." (PMID 36548081, 2023). "Consistently, the tumor suppression by Ube2c KO in the KrasG12D lung cancer model could be largely abrogated by simultaneous Deptor KO, indicating a causal relationship between UBE2C and DEPTOR." (PMID 36548081, 2023). "The growth suppression by UBE2C knockdown could be largely rescued by simultaneous DEPTOR knockdown in lung cancer cells." (PMID 36548081, 2023). "However, studies have also demonstrated that DEPTOR is overexpressed in many tumours, including breast, prostate and lung cancers, indicating that DEPTOR also acts as an oncogene during tumour growth." (PMID 32372061, 2020). "DEPTOR inhibits the EMT process by inhibiting the AKT/GSK3β/snail pathway in lung carcinoma cells." (PMID 31228948, 2019). "mTORC signals are negative regulators of autophagy, and UBE2C-mediated autophagy repression contributes to malignant phenotypes of lung cancer cells, suggesting that autophagy modulation via the DEPTOR/mTORC axis could be actively involved in the growth-suppressing effect of UBE2C knockdown as well." (PMID 36548081, 2023). "In this mechanism, DEPTOR overexpression leads to inhibition of MTOC1 and activation of AKT pathway expression, while DEPTOR was found to be a tumor suppressor in pancreatic cancer, ESCC, lung cancer, triple-negative breast cancer, and B-ALL." (PMID 40650680, 2025). "In multiple lung cancer cell lines, knockdown of either UBE2C or CDH1 significantly extended the protein half-life of DEPTOR, while ectopic overexpression of UBE2C or CDH1 shortened the protein half-life of DEPTOR." (PMID 36548081, 2023). "Taken together, our results indicated that by increasing DEPTOR levels, Ube2c deletion inactivated mTORC signaling to inhibit KrasG12D-induced lung tumorigenesis, and suggested that UBE2C could be an effective therapeutic target for management of lung cancer associated with Kras mutation." (PMID 36548081, 2023). "Given that DEPTOR knockdown rescued the phenotypes induced by UBE2C knockdown in in vitro cell culture models, we then determined in vivo whether Deptor KO could rescue the suppression of lung tumorigenesis by Ube2c KO in the KrasG12D mouse lung cancer model." (PMID 36548081, 2023).
hepatocellular carcinoma (8 papers, 2012 to 2025). A malignant tumor that arises from hepatocytes. "DEPTOR overexpression was reported in hepatocellular carcinoma tissues from HCC patients and its expression was linked to the poor survivability of HCC patients." (PMID 26992219, 2016). "DEPTOR overexpression in multiple myeloma, as well as in hepatocellular carcinoma and thyroid carcinoma, is correlated with poor prognosis." (PMID 31685947, 2020). "The AMPK activation by metformin enhances the binding of DEPTOR and mTOR by increasing DEPTOR production and inhibiting proteasomal degradation, thereby interfering with the downstream target p70-S6 kinase and ribosomal protein S6 and inhibiting the proliferation of hepatocellular carcinoma cells." (PMID 38192642, 2023).
Obesity (8 papers, 2015 to 2025). Accumulation of substantial excess body fat. "In this study, we found that Deptor is part of a quantitative trait locus linked to obesity/leanness in mice, with DEPTOR levels being elevated in WAT of obese animals." (PMID 36535626, 2023). "In animal models, DEPTOR overexpression is responsible for the accumulation of white adipose tissue, and in humans, it is associated with some degree of obesity." (PMID 26640797, 2015). "Importantly, we identified that the CEBPB-LAP places itself upstream of Notch1 and DEPTOR signaling nodes which are additionally implicated in obesity and adipogenesis." (PMID 41282072, 2025). "DEPTOR expression levels are increased in white adipose tissue in obesity and DEPTOR promotes adipogenesis by tuning down mTORC1 feedback control and thereby activating AKT signaling." (PMID 34519268, 2021). "Paradoxically, systemic overexpression of DEPTOR (periphery and brain) was shown to protect mice against the development of obesity by affecting the mediobasal hypothalamic regulation of energy balance." (PMID 28462079, 2017). "For example, peripheral overexpression of DEPTOR promotes diet-induced obesity whereas its overexpression in the mediobasal hypothalamus protects mice against body weight gain." (PMID 28462079, 2017). "Therefore, a CEBPB and C19MC-driven Mon-gene-signature regulates the podosomal belt, lipid droplet, HBV, and DEPTOR mRNA dynamics to genetically link obesity, and neurodegeneration at the cellular level." (PMID 41282072, 2025). "DEPTOR plays central roles in cancer, obesity, and immunodeficiency." (PMID 34519268, 2021). "Overexpression of DEPTOR (DEP-domain containing mTOR-interacting protein), a negative regulator of the mTOR/S6K pathway, specifically using a viral vector in the mediobasal hypothalamus, prevents HFD-induced obesity and improves glucose metabolism." (PMID 30875909, 2019). "We also highlight context-specific regulatory effects for genes involved in metabolic (e.g. obesity, NTRK2,) and neurological (e.g. schizophrenia, MAN2A1,) diseases, and for genes with a role in biological processes such as adipogenesis (e.g. DEPTOR,)." (PMID 37543566, 2023).
colorectal cancer (6 papers, 2016 to 2025). A primary or metastatic malignant neoplasm that affects the colon or rectum. "Wang also reported that DEPTOR was a novel target of Wnt/b-Catenin/c-Myc and contributed to colorectal cancer cell growth." (PMID 32372061, 2020). "Nevertheless, DEPTOR knockdown in colorectal cancer cells reduced cell proliferation and induced differentiation, raising the possibility that DEPTOR can promote tumorigenesis in other epithelial cancers." (PMID 32630372, 2020). "In clinical investigations, downregualtion of DEPTOR has been found in pancreatic and colorectal cancer, which makes it a potential marker for prognosis of tumor patients." (PMID 26893358, 2016). "DEPTOR has also been shown to exert mTORC1/2-independent functions in the nucleus as a transcriptional regulator in multiple myeloma cells and is a transcriptional target of WNT/β-catenin/MYC signaling in colorectal cancer cells, adding further complexity to PI3K-AKT-mTOR and WNT pathway crosstalk." (PMID 32630372, 2020).
cervical squamous cell carcinoma (5 papers, 2016 to 2021). A squamous cell carcinoma arising from the cervical epithelium. "For example, in cervical squamous cell carcinoma cells DEPTOR induced cell survival, and overexpression of DEPTOR correlated with poor prognosis in differentiated thyroid carcinoma." (PMID 34572083, 2021). "The present study reveals a vital role for DEPTOR in survival of cervical squamous cell carcinoma (SCC)." (PMID 26992219, 2016). "However, contrary to our finding, it was previously reported that in cervical squamous cell carcinoma cells, DEPTOR silencing activated p38 MAPK in an mTOR-independent manner, promoting cell apoptosis." (PMID 29670094, 2018).
ovarian carcinoma (5 papers, 2014 to 2024). A malignant neoplasm originating from the surface ovarian epithelium. "Studies suggest increased DEPTOR regulation as a positive prognostic marker in ovarian cancer, indicating the DEPTOR gene’s role in suppressing endometrioid ovarian cancer." (PMID 38584599, 2024). "We, and others, have also shown that DEPTOR is overexpressed in chemotherapy-resistant ovarian cancer cell lines." (PMID 34572083, 2021). "Moreover, DEPTOR has been shown to be downregulated in malignancies of the prostate, bladder, head and neck, cervix and thyroid, whereas we have previously demonstrated the significant upregulation of DEPTOR in two paclitaxel-resistant ovarian cancer cell lines when compared to the parental ones." (PMID 25119265, 2014).
pancreatic cancer (5 papers, 2014 to 2025). "Our study suggests that DEPTOR acts as a tumor suppressor in pancreatic cancer and its loss may contribute to the initiation and progression of pancreatic tumorigenesis." (PMID 25544749, 2014). "Taken together, these data suggest that DEPTOR has a tumor suppressive activity against pancreatic cancer cells, and its loss of expression may contribute to pancreatic tumorigenesis." (PMID 25544749, 2014). "As mTOR activation is reported to be the hall mark of several cancers, DEPTOR in general should act as tumor suppressor and its expression was reported to have growth suppression effects in pancreatic cancer cells." (PMID 26992219, 2016). "Ectopic expression of DEPTOR in pancreatic cancer cells suppressed their growth in monolayer culture and in soft agar, and decreased clonogenic survival by inducing apoptosis and growth arrest, likely through inactivation of mTORC1 signal." (PMID 25544749, 2014). "In liver and pancreas cancer models, UTX can control the expression of negative regulators of mTOR such as DEPTOR, and its disruption prevents their transcription and facilitates tumorigenesis through increased mTORC1 activity." (PMID 37261974, 2023). "The role of DEPTOR in the growth and survival of pancreatic cancer cells has not previously been determined." (PMID 25544749, 2014). "Although DEPTOR has been shown to inhibit mTOR activity and may act as a tumor suppressor in some cell culture settings, it has not been previously tested whether and how DEPTOR plays a role in pancreatic cancer." (PMID 25544749, 2014).
esophageal squamous cell carcinoma (4 papers, 2016 to 2025). Esophageal squamous cell carcinoma (ESCC) is a type of esophageal carcinoma (EC) that can affect any part of the esophagus, but is usually located in the upper or middle third. "However, the function of DEPTOR in the development of esophageal squamous cell carcinoma (ESCC) is still unclear." (PMID 26893358, 2016). "Thus, our study suggests that DEPTOR inhibits the tumorigenesis of ESCC cells and might serve as a potential therapeutic target or prognostic marker for human patients with esophageal squamous cell carcinoma." (PMID 26893358, 2016).
gastric cancer (4 papers, 2016 to 2025). A primary or metastatic malignant neoplasm involving the stomach. "Moreover, PUM1 causes metabolic reprogramming in gastric cancer by post-transcriptionally regulating the DEP domain-containing mTOR-interacting protein (DEPTOR)." (PMID 41155797, 2025). "Pumilio 1 (PUM1), an RNA binding protein, induces metabolic reprogramming through post‐transcriptional regulation of DEP domain‐containing mammalian TOR (mTOR)‐interacting protein (DEPTOR) in gastric cancer (GC)." (PMID 37469018, 2023). "Among these inhibitor, PP242 is a dual mTORC1 and mTORC2 inhibitor that similar with DEPTOR, which has been reported to suppress proliferation, metastasis, and angiogenesis of gastric cancer cells through inhibition of the PI3K/AKT/mTOR pathway." (PMID 26893358, 2016).
Insulin resistance (4 papers, 2017 to 2023). Increased resistance towards insulin, that is, diminished effectiveness of insulin in reducing blood glucose levels. "In addition to cancer, our model predictions also support recent biological findings of the in vivo impact of DEPTOR loss or overexpression in the context of cellular metabolism, insulin resistance and obesity." (PMID 29330362, 2018). "Rather, overexpression of DEPTOR in these neurons resulted in liver steatosis and insulin resistance following a high-fat diet." (PMID 28462079, 2017). "In that case, it was reported that DEPTOR overexpression promotes glycolysis and protects mice from developing insulin resistance." (PMID 28462079, 2017).